IL2 (interleukin 2)
Diseases named in the same sentence as IL2 in open-access papers (continued):
Sharing a sentence is not in itself a finding about the gene and the disease.
systemic lupus erythematosus (continued). "This table summarizes the key characteristics and results of studies evaluating interleukin-2 (IL-2) treatment in patients with systemic lupus erythematosus (SLE)." (PMID 40452697, 2025). "Preclinical investigations and initial clinical trials have shown evidence that supports the effectiveness and safety of low-dose IL-2 treatment in systemic lupus erythematosus (SLE)." (PMID 39371877, 2024). "However, consequences due to increased expression of NFAT are not as predictable; due to the overexpression of NFAT and its binding to its target promoters, CD40L gene is more easily activated, whereas production of IL-2 is observed to be lower in lupus T-cells." (PMID 37215992, 2023). "Our previous clinical trials of low‐dose IL‐2 therapy in systemic lupus erythematosus and Sjogren's syndrome have demonstrated that it could enhance antigen‐independent expansions of Treg cells, thus providing a strategy to improve the poor clonal expansion of Treg cells in autoimmune uveitis." (PMID 37720629, 2023). "In addition, MRL/lpr lupus-prone mice knocked out for IL-23 receptors (IL-23R) revealed less severe LN, which was mechanistically explained by the restoration of IL-2 and a decrease in IL-17 production by T cells, together with reduced TFH and APCs, and reduced anti-dsDNA levels." (PMID 35326431, 2022). "Low-dose IL-2 therapy has been used in the clinical treatment of autoimmune diseases such as systemic lupus erythematosus (SLE), rheumatoid arthritis (RA) and T1D and achieved excellent effects." (PMID 35874688, 2022). "In human clinical studies, low dose of IL-2 (LDIL-2) has been used in small cohorts of patients with systemic lupus erythematosus (SLE), chronic graft versus host disease (GVHD), Type 1 diabetes (T1D), and Hepatitis C virus (HCV) related vasculitis." (PMID 35665339, 2022). "From an immune-pathophysiological point of view systemic lupus erythematosus (SLE) appeared to be an ideal and promising candidate disease for a therapeutic intervention by low-dose IL-2 therapy." (PMID 33868284, 2021). "Taken together, intrarenal Treg of lupus prone mice could be influenced by a short-term IL-2 treatment by means of numbers, phenotype and proliferation, whereas with the exception of an increase in the frequency of CD25+ Tcon, intrarenal Tcon were almost unaffected." (PMID 31614462, 2019). "The reduced availability of IL-2 in the inflamed kidneys of (NZB × NZW) F1 lupus-prone mice could therefore result in impaired Treg growth and survival thereby impeding their capability to adequately control the progressive hyperactivity of intrarenal effector/memory Tcon." (PMID 31614462, 2019). "Recent research has further revealed that lupus B cells with enhanced PD-1 expression exhibit functionally reduced proliferation along with reduced PD-L1 up-regulation capacity upon stimulation by interleukin-2(IL-2)/IL-10, anti-B cell receptor (anti-BCR), CpG, and CD40L." (PMID 31597242, 2019). "Up-regulated cyclic adenosine 5'-monophosphate response element modulator α (CREMα) which can inhibit IL-2 and induce IL-17A in T cells plays a critical role in the pathogenesis of systemic lupus erythematosus (SLE)." (PMID 27904655, 2016). "High serum IL-2 levels are also associated with conditions such as scleroderma, progression of gastric and non-cell lung cancer, and certain neoplastic diseases, while elevated IFN-γ is implicated in pathology of diseases such as systemic lupus erythematosus, and multiple sclerosis." (PMID 26192591, 2015). "In previous studies, the effectiveness of low-dose IL-2 on Treg cell proliferation and disease remission in psoriatic arthritis (PsA), systemic lupus erythematosus (SLE), and Sjögren’s syndrome (SS) has been demonstrated, but side effects have not been evaluated." (PMID 39981233, 2025).
systemic lupus erythematosus (continued). "The ratio of TFR cells to TFH cells may change in certain disease states, such as in systemic lupus erythematosus (SLE), where low-dose IL-2 therapy can inhibit TFH cells and expand TFR cells, thereby regulating pathogenic humoral immunity." (PMID 40027134, 2025). "In vivo Treg expansion by low-dose IL-2 has initially shown clinical success in a few conditions, such as GVHD, hepatitis C virus–induced (HCV-induced) vasculitis, and systemic lupus erythematosus." (PMID 38426492, 2024). "IL-2 limits CD4 Tfh cell and GC formation and also promotes several downregulatory mechanisms of potential importance in lupus, including formation and/or maintenance of CD8 CTL, Th1 CD4 T cells, and CD4 Tregs." (PMID 38915570, 2024). "Treatment with low-dose IL-2 therapy has been shown to increase the Tregs population and proven to be clinically effective in a few trials on type 1 diabetes mellitus, graft versus host disease, systemic lupus erythematosus (SLE), and rheumatoid arthritis." (PMID 39328700, 2024). "In a study of identical twins discordant for lupus, defective cytolytic CD56+ natural killer cell killing was observed in both unaffected and affected twins, consistent with a pre-existing IL-2-dependent immune defect." (PMID 38915570, 2024). "Vitamin E has antioxidant and anti-inflammatory effects and, because of its anti-inflammatory effect, seeks to reduce IL-2, IL-4, and TNF-α, which can be effective in lupus." (PMID 37511964, 2023). "In ongoing clinical trials, the safety and efficacy of a human IL-2 mutein Fc fusion protein (Efavaleukin Alfa) to selectively stimulate Tregs is being evaluated in patients with GvHD (NCT03422627) and systemic lupus erythematosus (NCT03451422)." (PMID 36675265, 2023). "TGP increased the number and percentage of Treg cells in lupus CD4+ T cells and increased IFN-γ and IL-2 expression." (PMID 37511964, 2023). "In our present study, based on mice models, we found that GDF-15 alleviated lupus by reducing renal damage, reversing CD8+, CD19+, and TH2 cells dysregulation, inhibiting production of IL-1β, IL-2, IL-4, IL-21, IL-22, ANA, and total IgG." (PMID 35911685, 2022). "Here, the pathophysiology of lupus T cells and current, as well as ongoing, therapeutic approaches of SLE that involve low-dose IL-2 administration will be highlighted." (PMID 35326431, 2022). "In murine models, low-dose IL-2 therapy was found to be effective in the treatment of NOD mice and female NZB/W F1 lupus-prone mice." (PMID 35326431, 2022). "Percentages of CD8+, CD11b+, CD19+, CD11C+ cells, TH2 cells, and pro-inflammatory cytokines (IL-1β, IL-2, IL-4, IL-21, and IL-22) were reduced after GDF-15 treatment in lupus mice." (PMID 35911685, 2022). "Furthermore, clinical trials investigating the effect of LD IL-2 in active systemic lupus erythematosus (SLE) have been successful in mitigating refractory phenotypes to standard therapy." (PMID 35954285, 2022). "For example, anti-CD4 and anti-CD2-coated poly(lactic-co-glycolic) acid (PLGA) nanoparticles loaded with IL-2 and TGFβ expanded Treg cells in vitro and in vivo in the BDF1 lupus pre-clinical model." (PMID 34335564, 2021). "To examine its influence on infection, we retrospectively studied 665 patients with systemic lupus erythematosus (SLE) including about one third receiving Ld-IL2 therapy, where Ld-IL2 therapy was found beneficial in reducing the incidence of infections." (PMID 34618873, 2021). "On the other hand, IL-2 expanded IL-13-producing CD8+ T cells that also expressed IL-5 and IFN-γ in lupus patients via a signaling pathway likely involving the activation of STAT6-GATA-3 axis, but not STAT5." (PMID 33763079, 2021). "Thus low‐dose of IL‐2 has been found to have a broad therapeutic potential in many autoimmune and inflammatory diseases, like systemic lupus erythematosus (SLE), sjogren syndrome, and various kinds of tumors." (PMID 33098626, 2020).
systemic lupus erythematosus (continued). "Notably, therapeutic administration of JES6/IL-2 complexes in a spontaneous model of lupus was shown to ameliorate ICGN, arguing in favor for our hypothesis that stimulation of donor CD4+ T cells by JES6/IL-2 complexes canceled out the beneficial effect of Treg stimulation." (PMID 29670626, 2018). "Further research is needed to investigate the effectiveness of combining low-dose IL-2 with standard immunosuppressive medications, such as mycophenolate mofetil or hydroxychloroquine, in order to identify the most effective treatment methods for patients with systemic lupus erythematosus (SLE)." (PMID 39371877, 2024). "Clinical applications of low-dose IL-2 therapy have shown promise, demonstrating safety and effectiveness in treating systemic lupus erythematosus and influencing Th17/Treg rather than Th1/Th2 cell balance." (PMID 38408917, 2024). "A primary, pre-existing defect in IL-2 has been suspected, but remains difficult to address in either spontaneous murine or human lupus since it is not clear when disease is initiated." (PMID 38915570, 2024). "It is important to note that lupus CD4+ T cells were primed to receive and activate IL-2 signaling as evidenced by the upregulation of CD25 and enhanced IL-2-induced STAT5 phosphorylation during Treg differentiation even though the CD4+CD25+FOXP3+ Treg population was depleted in SLE patients." (PMID 33763079, 2021). "In the clinic, low-dose IL-2 therapy has been shown to selectively expand FOXP3 Tregs and used successfully to treat chronic GVHD, hepatitis C virus–induced vasculitis, systemic lupus erythematosus (SLE), and type 1 diabetes." (PMID 34512640, 2021). "Serum proinflammatory cytokines, including IL-17a, IFN-γ, IL-6, TNF, and IL-2, were significantly increased, while the anti-inflammatory cytokine IL-10 was significantly decreased in sodium chloride-pretreated BMDC-ALD-DNA-induced lupus mice." (PMID 32296043, 2020). "A dose-dependent increase in the frequency of circulating NK cells in BDF1 lupus mice that had received CD2-targeted NPs loaded with IL-2/TGF-β was not seen in non-lupus mice or in mice that had received uncoated NPs." (PMID 33391260, 2020). "Another autoimmune ailment that can lead to ESRD is systemic lupus erythematosus (SLE), where defects in IL-2 production and Tregs have been shown to contribute to pathogenesis, and IL-2-based approaches to enhance Tregs have been shown to be beneficial for SLE but not for lupus nephritis." (PMID 31191312, 2019). "In a mouse model of systemic lupus erythematosus (SLE), it was found that treatment with pan-HDACi trichostatin A (TSA) led to a decrease in mRNA expression of various inflammatory cytokines such as IL-6, IL-2, IL-10, and IFNγ." (PMID 31067680, 2019). "The application of HDAC inhibitors, such as trichostatin A (TSA), leads to a wide-ranged acetylation of histones and thus reduces the expression level of those inflammatory cytokines, such as IL-2, interferon (IFN)-γ, and IL-6, as well as alleviate the symptoms of lupus-prone mice." (PMID 28785369, 2017). "We examined the components of the inflammatory cells in the lupus mice and found that the percentages of CD4+ T, IL-2+, IL-17+ cells in peripheral blood were significantly higher in B7-H4-KO BMDCs-ALD-DNA induced lupus mice than that in WT BMDCs-ALD-DNA induced lupus mice." (PMID 29321778, 2017). "Unlike our finding in murine lupus models, human lupus peripheral blood T cells had decreased miR-31 expression, which correlated with reduced IL2 production in human lupus T cells." (PMID 24175965, 2013). "If the tolerogenic effects of IL-2 on Treg production require TGF-β, then a TGF-β deficiency could contribute to the lack of efficacy observed in lupus clinical trials involving IL-2." (PMID 41368646, 2025).
systemic lupus erythematosus (continued). "Additionally, enhancing the function or expansion of regulatory T cells (Tregs), which are vital for maintaining immune tolerance, has been studied in conditions like systemic lupus erythematosus (SLE) and type 1 diabetes, with therapies such as low-dose IL-2 showing promise." (PMID 40006751, 2025). "Finally, within diabetes and lupus wound models, dermal wounds did not heal in IL-2 knockout models." (PMID 38830847, 2024). "Interestingly, current updated advancements have comprehensively clarified more about the new hypothesis of IL-2 in SLE treatment and T-bet involved in lupus development by regulating B cells." (PMID 38164134, 2023). "FVB/Fas−/− lupus-like mice had lymphadenopathy, splenomegaly, high proportion of CD4−CD8− T cells, IFNγ-producing T cells, and low proportion of Treg cells, and addition of IL-2 (25 ng/g bodyweight every 5 days, five times) restored the number of Treg cells and upregulated IFNγ expression." (PMID 38164134, 2023). "Moreover, T cell-targeted nanoparticles loaded with transforming growth factor β (TGF-β) and IL-2 could induce CD4+ and CD8+ Treg cells to inhibit murine lupus." (PMID 34539413, 2021). "IL2/IL4 and IL2/IL10 ratios have been repeatedly used as markers of inflammation and tissue injury in Systemic Lupus Erythematosus (SLE), or as an indication of cytokine imbalance in vitiligo, also in athletes." (PMID 34271953, 2021). "Clinical studies have shown that many immune-related diseases, such as systemic lupus erythematosus (SLE), rheumatoid arthritis, polymyositis/dermatomyositis, Sjögren’s syndrome, Treg cell defects, and Th17/Treg cell imbalance, may benefit from low-dose IL-2 treatment." (PMID 37596509, 2023). "Low-dose IL-2 can directionally induce the augmentation of Tregs and has been applied in clinical trials for the treatment of AID such as systemic lupus erythematosus (SLE)." (PMID 37497009, 2023). "Moreover, in contrast to cGvHD, spontaneous lupus is a slowly developing disease that is not driven by a high number of alloreactive donor cell populations and, therefore, might be more susceptible to therapeutic intervention with JES6/IL-2 complexes." (PMID 29670626, 2018). "Freshly isolated CD4+ T lymphocytes from pristane-induced lupus mice were activated with anti-CD3/CD28 antibodies (3 μg/ml) and interleukin-2 (IL-2) (200 U/ml) with or without resveratrol (0, 10, 20, 40, or 80 μM)." (PMID 25501752, 2014).
influenza (166 papers, 2008 to 2026). An acute viral infection of the respiratory tract, occurring in isolated cases, in epidemics, or in pandemics; it is caused by serologically different strains of viruses (influenzaviruses) designated A, B, and C, has a 3-day incubation period, and usually lasts for 3 to 10 days. "While the role of elevated TNF‐alpha in influenza pathogenesis has been well‐studied, the association between an overactive IL‐2 response and morbidity in influenza infection is less clear." (PMID 30156030, 2019). "Reduced IL-2 production by CD4+ T-cells has been associated with decreased antibody responses to influenza vaccination in older people." (PMID 24842313, 2014). "More pertinently, IL-2 has also been implicated in the expansion of CD8+ T-cells upon influenza infection and as such may be an important contributor to cellular immunity against infection." (PMID 33498370, 2021). "In addition to these IL-2–dependent and Ab-dependent responses, NK cell responses to innate cytokines were also enhanced after influenza vaccination; this was associated with proliferation of CD57− NK cells and was most evident in HCMV+ subjects." (PMID 27233958, 2016). "Compared to the moderate enhancement of CD8+ T cell activation in influenza infection, IL-2 treatment in acute LCMV infection caused a stronger activation of CD8+ T cells, which might break down the immune tolerance and result in CD8+ T cell-mediated tissue immunopathology." (PMID 34618873, 2021). "Future studies could test whether the variable cytokine expression in the human anti-influenza response was related to allelic expression, by analyzing influenza-specific cells for the expression of individual SNP-marked alleles of IL-2 in subjects pre-screened for SNP heterozygosity." (PMID 24788814, 2014). "We measured IL-2 production after antigen-specific stimulation with either S-, Nc-, M- or cytomegalovirus-, Epstein–Barr virus- and influenza (CEF)-specific peptide pools." (PMID 41324571, 2025). "Here, we describe the role of BLIMP1 as a negative regulator of IL-2 signaling in mouse and human T cells and in influenza infection and colitis mouse models, as well as in primary cells from patients with ATL." (PMID 40680114, 2025). "IL-2 signaling has been shown to be highest at the peak of influenza infection in various CD4+ T cell populations, such as TFH, TFR, TEFF, and Treg cells." (PMID 40680114, 2025). "Different cytokine profiles were observed compared to influenza and bacterial pneumonia, with IL-2, IL-1β, IL-8, IL-10, CXCL10, and MCP-1 being highest in the AdV group, while free TGF-β1 was lowest in the AdV group." (PMID 39858309, 2025). "In COPD patients before the vaccination against influenza, a strong inverse correlation between the pro-inflammatory cytokine IL-2 and the frequency of outpatient visits was revealed (r = -0.81; p<0.05)." (PMID 39937802, 2025). "We therefore studied the role of BLIMP1 in regulating IL-2 signaling in CD4+ T cells from influenza-infected mice." (PMID 40680114, 2025). "We evaluated serum concentrations of seven cytokines (IL-2, IL-4, IL-6, IL-10, TNFα, IFNγ, and IL-17a) as potential biomarkers for influenza severity in pregnant women." (PMID 40558593, 2025). "Tregs limit CD8+ T cell and NK cell proliferation via IL-10 and TGF-β production while promoting Tfh cell differentiation in CD4+ T cells by sequestering IL-2, thereby enhancing germinal center B cell responses in influenza infections." (PMID 40872830, 2025). "Overall, these results are consistent with BLIMP1 controlling influenza infection, at least in part, by regulating IL-2 signaling in CD4+ T cells." (PMID 40680114, 2025). "The interplay between smoking, IL-2 dynamics, and influenza pathogenesis warrants further exploration, particularly concerning long-term immune dysregulation and disease outcomes." (PMID 39456722, 2024).